AQP4 (aquaporin 4)
Diseases named in the same sentence as AQP4 in open-access papers (continued):
Sharing a sentence is not in itself a finding about the gene and the disease.
cerebral (6 papers, 2012 to 2025). "AQP4 is a member of the water channel family, whose downregulation plays a neuroprotective role in middle cerebral artery occlusion rats by repressing oxidative stress and inflammatory response." (PMID 34362382, 2021). "Thus, we postulate that the reduction of Aqp4 polarization observed to occur in cortical astrocytes partially protected the ischemic cortex from local formation of cerebral edema." (PMID 26419740, 2015). "Down-regulation of AQP4 could be a way in which HS ameliorates cerebral edema." (PMID 23036239, 2012). "While several lines of evidence have suggested that AQP4 plays important roles in maintaining BBB integrity and edema, research regarding the effects of AQP4 on BBB injury and cerebral edema remains controversial." (PMID 29599893, 2018).
migraine (6 papers, 2018 to 2025). "Among the various isoforms of aquaporin, disorders affecting aquaporin 4 (AQP4) might be associated with both migraines and inner ear diseases." (PMID 30250448, 2018). "Studies in animal models have demonstrated that pharmacological inhibition of AQP4 worsens migraine symptoms, seen through worsened hyperalgesia." (PMID 41462992, 2025). "Mice in the migraine model showed decreased glymphatic influx with reduced aquaporin-4 expression and impaired polarisation, suggesting glymphatic dysfunction in the migraine mouse model." (PMID 39039435, 2024). "This highlights the critical role of AQP4 in maintaining glymphatic function in migraine." (PMID 41462992, 2025). "Conditions involving an overlap of the pathophysiologies of MD and migraine, such as disorders affecting aquaporin 4, may be also related to worse saccular dysfunction." (PMID 37122301, 2023).
mood disorder (6 papers, 2021 to 2026). A cognitive disorder a disturbance in which the person's mood is hypothesized to be the main underlying feature. "We propose that comorbid NMOSD and mood disorders share a neuropathological basis linked to AQP4-IgG-mediated cascades." (PMID 41586066, 2026). "These case reports suggest a bidirectional association between NMOSD and mood disorders, likely mediated by AQP4-IgG-driven neuroinflammation." (PMID 41586066, 2026). "Based on these experiments, abnormal astrocytes and AQP4 expression are very common characteristics of the pathology of mood disorders, which may be the main cause of glymphatic system dysfunction, but the contradictory experimental results require further integration and analysis." (PMID 35547631, 2022). "These case reports suggest a bidirectional relationship between NMOSD and mood disorders, likely mediated by AQP4-IgG-driven neuroinflammatory responses." (PMID 41586066, 2026). "Dysregulated expression of astrocytic functional proteins, such as glutamate transporter-1 (GLT-1), aquaporin-4 (AQP4), and glutamine synthetase (GS), not only exacerbates mood disorders but also influences seizure thresholds." (PMID 40641625, 2025). "Both animal and human studies have reported suppressed glymphatic transport, abnormal astrocytes, and depolarized AQP4 in mood disorders." (PMID 34025481, 2021). "AQP4-IgG screening may serve as a critical tool to distinguish organic mood disorder from primary psychiatric conditions, particularly in patients with atypical neurological symptoms." (PMID 41586066, 2026). "Despite this, the authors concluded that ‘AQP4 may still play a role in the pathogenesis of mood disorders through various mechanisms of action such as altered AQP4 expression in the brain’." (PMID 40717781, 2025). "However, in an oligonucleotide microarray analysis and qPCR study of postmortem brain tissues from patients with mood disorder, the expression of the AQP4 gene U34646 was upregulated in the prefrontal cortex." (PMID 35547631, 2022). "Upregulated expression of AQP4 in the prefrontal cortex of patients with mood disorders." (PMID 34025481, 2021). "Significantly, suppressed glymphatic circulation, astrocytic abnormalities, and AQP4 depolarization are consistently reported in mood disorders, providing support for the posited hypothesis." (PMID 34025481, 2021). "Therefore, AQP4-dependent glymphatic system may serve as a new therapeutic target in mood disorders." (PMID 34025481, 2021). "Patients overlapped with AQP4-Ab-positive NMOSD presented abnormal behavior (11/18), mood disorders (6/18), psychosis (4/18), and agitation (2/18)." (PMID 35837405, 2022). "Even though direct evidence for glymphatic impairment in mood disorders is lacking, astrocytes and AQP4 abnormalities provide support to the hypothesis that glymphatic dysfunction functions as a bridge between sleep disturbance and mood disorders." (PMID 34025481, 2021).
myositis (6 papers, 2016 to 2023). "Remarkably, NMOSD was comorbid with myocarditis and myositis in a patient with antinuclear antibodies and anti-aquaporin 4 (AQP4) antibodies positivity." (PMID 37103032, 2023). "Furthermore, the report of mild myositis in EAE rats that received adoptively transferred AQP4-specific T-cells is also in agreement to our findings." (PMID 29951558, 2018). "This is consistent with the near absence, albeit for a few case reports of NMO-related myositis, of NMO pathology in peripheral organs in which AQP4 is expressed, including the skeletal muscle, stomach, kidney, airways, and exocrine glands." (PMID 27765056, 2016). "H&E staining revealed no infiltration of inflammatory cells in hind limb muscles of mice in different groups; hence, no AQP4-IgG-induced myositis in hind limbs of mice contributing to motor impairments." (PMID 32782018, 2020).
paroxysmal nocturnal hemoglobinuria (6 papers, 2021 to 2025). Paroxysmal nocturnal hemoglobinuria (PNH) is an acquired clonal hematopoietic stem cell disorder characterized by corpuscular hemolytic anemia, bone marrow failure and frequent thrombotic events. "These are eculizumab, an anti-C5 antibody, approved for AQP4+ NMOSD, generalized MG, as well as atypical hemolytic uremic syndrome (aHUS) and paroxysmal nocturnal hemoglobinuria (PNH)." (PMID 36032156, 2022).
psychosis (6 papers, 2015 to 2025). "Functional variants of the AQP4 gene have been linked to an increased risk of psychosis and more severe symptoms." (PMID 40896232, 2025). "Positivity for antibodies against aquaporin-4 (AQP4), a glial-expressed protein, was associated with neurological involvement, particularly psychosis and seizures." (PMID 41010387, 2025). "Specifically, reduced ALPS index values in patients relative to non-psychiatric controls align with a growing body of literature implicating astrocytic dysfunction, AQP4 misregulation, and elevated peripheral S100B levels in the acute phase of psychosis." (PMID 40896232, 2025). "Regardless, both studies reported significantly higher frequency of neurological involvement among AQP4 seropositive patients, and particularly psychosis and seizures." (PMID 41010387, 2025).
retinitis (6 papers, 2016 to 2023). Inflammation of the retina. "Thus, T‐cell‐mediated retinitis alone is not sufficient to induce an increase in INL volume while anti‐AQP4 antibodies in the presence of a T‐cell‐mediated retinitis result in INL swelling." (PMID 28058717, 2017). "The suppression of AQP-4 prevents the binding of HIF1α to the VEGF promoter, thus reducing hypoxia induced-retinal damage." (PMID 34681190, 2021).
syringomyelia (6 papers, 2016 to 2025). Syringomyelia is characterized by cerebrospinal fluid (CSF)-filled cavities (syrinx) inside the spinal cord, either as a result of a known cause (secondary syringomyelia, SS) or, more rarely, due to an unknown cause (primary syringomyelia, PS). "Aquaporin-4 (AQP4) has been implicated in post-traumatic syringomyelia (PTS), a disease characterised by the formation of fluid-filled cysts in the spinal cord." (PMID 37316571, 2023). "In mice suffering from posttraumatic syringomyelia, an increased AQP4 expression has been found, suggesting increased AQP4 expression as a driver of cyst formation." (PMID 35126070, 2021). "MRI of the spine revealed a syringomyelia extending from the C7 to T4 levels with serum positive anti-aquaporin-4 antibodies (AQP4-Ab) (indirect immunofluorescence on AQP4 transfected cells)." (PMID 30301458, 2018). "In an excitotoxic injury model of syringomyelia, AQP4 was upregulated around the enlarging syrinx 3 and 6 weeks post-surgery, which suggests AQP4 could play a critical role in PTS." (PMID 37316571, 2023). "Hemley and colleagues reported a significant increase in AQP4 expression at the level of syrinx in the post-traumatic syringomyelia model and suggested that there may be a relationship between AQP4 expression levels and fluid accumulation in the spinal cord." (PMID 30909935, 2019).
tauopathy (6 papers, 2020 to 2025). Neurodegenerative disorders involving deposition of abnormal tau protein isoforms (tau proteins) in neurons and glial cells in the brain. "Authors go on to show that deficiency in aquaporin 4 (AQP4), a channel protein expressed at the astrocytic endfeet that is essential for appropriate glymphatic function, aggravates tau hyperphosphorylation and neurodegeneration in a model of tauopathy." (PMID 37580702, 2023). "In a mouse model of tauopathy, glymphatic clearance was shown to be impaired, as was AQP4 polarization, both of which were correlated with increased tau protein deposition." (PMID 40806679, 2025). "Based on hippocampal AQP4 downregulation in both tauopathy models, we expect GFAPP301L have impaired memory." (PMID 38750510, 2024). "In this study we provide the first demonstration of impaired glymphatic function in an animal model of tauopathy and establish the essential role of AQP4 in the clearance of tau protein from the brain." (PMID 32705145, 2020). "Modifying glymphatic flow by pharmacologically targeting aquaporin-4 alters tau clearance, suggesting therapeutic potential against tauopathies." (PMID 32705145, 2020). "In addition, we recently demonstrated that AQP4 polarisation and glymphatic function were reduced in the brain of a transgenic mouse model of tauopathy, and that acute pharmacological blockade of AQP4 resulted in disrupted tau clearance from the brain." (PMID 38576025, 2024). "First, we demonstrate impaired CSF-ISF exchange and AQP4 polarization in a mouse model of tauopathy, suggesting that this clearance pathway may have the potential to exacerbate or even induce pathogenic accumulation of tau." (PMID 32705145, 2020). "Notably, AQP4 polarization was also found to be impaired in brain regions affected by tauopathy." (PMID 40806679, 2025). "Likewise, we previously provided further evidence suggesting a strong relationship between glymphatic function and tau accumulation, demonstrating reduced AQP4 perivascular localisation, decreased CSF/ISF exchange and impaired glymphatic inflow and clearance of tau in a mouse model of tauopathy." (PMID 38576025, 2024).
acute transverse myelitis (5 papers, 2022 to 2025). Acute transverse myelitis (ATM) is an inflammatory demyelinating disorder of the spinal cord that can be either idiopathic (IATM) or secondary to a known cause (SATM). "Among 60 AQP4-IgG-positive NMOSD patients, the most common was acute transverse myelitis, found in 35 cases (58.3%), followed by cerebral syndrome in 15 cases (25.0%)." (PMID 38259484, 2023). "MRI demonstrated a central thoracic cord lesion at T11, consistent with acute transverse myelitis, while serum AQP4 and MOG antibodies were negative." (PMID 41441534, 2025).
autism (5 papers, 2010 to 2024). Persistent deficits in social interaction and communication and interaction as well as a markedly restricted repertoire of activity and interest as well as repetitive patterns of behavior. "In addition to GFAP, altered expression of AQP4 has been associated with this neurologic disease; in particular AQP4 expression was decreased in cerebellum of subjects with autism." (PMID 21119878, 2010). "Other astrocytic abnormalities have also been observed in the brains of individuals with autism, including reduced protein levels of aquaporin 4 (AQP4) within the cerebellum together with elevated connexin 43 (CNX43) seen in the superior frontal cortex." (PMID 29234492, 2017).
Blindness (5 papers, 2013 to 2024). Blindness is the condition of lacking visual perception defined as a profound reduction in visual perception. "Patients with AQP4-IgG related ON (AQP4-ON) have worse vision and usually develop blindness, while patients with MOG-ON have a higher recurrence rate." (PMID 36969199, 2023).
brain cancer (5 papers, 2013 to 2022). A primary or metastatic malignant neoplasm affecting the brain. "A pan-cancer analysis is necessary for further exploring how AQP4 contributes toward maintaining immune homeostasis, in addition to its key function in tumorigenesis across human brain cancers." (PMID 34113257, 2021). "Recognition of AQP4-related therapy may open a new avenue for developing more specific targeted treatment for brain cancers." (PMID 36523816, 2022). "Interestingly, ours investigation found that other tumors expressed AQP4 to a lower degree compared to brain cancers such as GBM and LGG, implicating AQP4 in brain cancer tumorigenesis." (PMID 34113257, 2021). "Our study provides robust evidence supporting AQP4 as a new candidate for brain cancer treatment." (PMID 34113257, 2021). "Recognition of AQP4-specific inhibitors may open a new avenue for developing more specific targeted treatment for brain cancers." (PMID 34113257, 2021). "Our previous research indicated that AQP4 could be was found in high concentrations in brain cancer tissues and that AQP4 could also impact the overall survival of cancer patients." (PMID 34113257, 2021). "However, the roles of AQP4 in immunity, as well as in various other brain cancers have not been identified systematically." (PMID 34113257, 2021).
Duchenne muscular dystrophy (5 papers, 2011 to 2023). Duchenne muscular dystrophy (DMD) is a neuromuscular disease characterized by rapidly progressive muscle weakness and wasting due to degeneration of skeletal, smooth and cardiac muscle. "In contrast, Duchenne muscular dystrophy (DMD) is accompanied by AQP-4 dysfunction and also associated with excess β-amyloid accumulation." (PMID 28820467, 2017). "Due to its close association with α-syntrophin, which in turn facilitates interaction with the DAPC, several groups studied the expression patterns of α-syntrophin and AQP4 in Duchenne muscular dystrophy (DMD), which is caused by mutations in the dystrophin gene." (PMID 36675000, 2023). "For example, the dystrophin-deficient mdx mouse, an animal model of Duchenne muscular dystrophy (DMD), showed reduced AQP4 expression in muscle cells, indicating that AQP4 interacts with the dystrophin-associated complex DAP." (PMID 29039751, 2017). "For example, AQP4 is strongly reduced in skeletal muscle of Duchenne muscular dystrophy (DMD) patients as well as in the sarcolemma of the mdx mouse, an animal model of the disease." (PMID 21552523, 2011). "Since the discovery of AQP4, several studies have highlighted reduced AQP4 levels in Duchenne muscular dystrophy (DMD) patients and mouse models, and other neuromuscular disorders (NMDs) such as sarcoglycanopathies and dysferlinopathies." (PMID 36675000, 2023).
Gliosis (5 papers, 2014 to 2025). Gliosis is the focal proliferation of glial cells in the central nervous system. "To assess periventricular scarring and compromised CSF–interstitial fluid homeostasis in our neuraminidase-induced gliosis model, we analyzed aquaporin-4 (AQP4) expression patterns." (PMID 24341850, 2014).
Hyperammonemia (5 papers, 2021 to 2025). An increased concentration of ammonia in the blood. "Hyperammonemia over-activates the Na-K-2Cl cotransporter (NCCa-ATP) channel, increases ionic influx into the astrocyte, alters the water concentration gradient, and activates aquaporin 4 (AQP4) water channels, causing astrocyte swelling and brain edema." (PMID 35624703, 2022). "Several mechanisms have been suggested to correlate the hyperammonemia and the increase in brain astrocytic AQP4 channels." (PMID 39556255, 2024). "It was reported that ammonia- treated cultured astrocytes revealed a significant increase in the AQP4 protein expression as well as astrocytes swelling, suggesting the role of AQP4 channels in astrocytic swelling in hyperammonemia." (PMID 39556255, 2024). "Hyperammonemia led to limited effects on Cx43 and AQP4 expression, the relevance of these minimal changes should be viewed with caution." (PMID 33765917, 2021). "Secondly, hyperammonemia-induced neuro-inflammation/ microglia activation may also upregulate astrocytic AQP4 protein expression in the brain and subsequent cellular edema." (PMID 39556255, 2024). "Limitation of our study was that only one method was used for the detection of Cx43 and AQP4 expression under hyperammonemia in the co-culture model, e.g. additional quantitative real-time mRNA expression analysis could be useful and can be focus of future projects." (PMID 33765917, 2021). "Another investigation on ALF rats found that AQP4 expression did not coincide with the degree of cerebral edema or hyperammonemia." (PMID 36060277, 2022). "Emerging evidence suggests that non-hepatic hyperammonemia enhances aquaporin-4 (AQP4) expression in astrocytes via the gut-microbiota-brain axis (MGBA), inducing astrocyte edema, decreasing cerebral blood flow, and causing neuronal damage, leading to worsening of SAE." (PMID 40433666, 2025).